TIGIT (T cell immunoreceptor with Ig and ITIM domains)
Diseases named in the same sentence as TIGIT in open-access papers (continued):
Sharing a sentence is not in itself a finding about the gene and the disease.
cancer (continued). "Research utilizing single-cell data indicates that chemotherapy significantly alters the TME in PDAC, potentially contributing to resistance against immunotherapy by diminishing the interactions between TIGIT on CD8+ T cells and its receptor on cancer cells." (PMID 40075563, 2025). "Because of the limited efficacy of blocking TIGIT alone, these approaches to targeting TIGIT should be flexibly combined with other immunotherapies, such as anti-PD-1/LAG-3 or cancer vaccines." (PMID 40890162, 2025). "Investigating immune checkpoint receptors like TIGIT, VISTA, GITR, TIM-3 and STING stands at the forefront of cancer research, unveiling new pathways to adjust the immune system’s reaction to tumors." (PMID 40777027, 2025). "While anti-CTLA4 and anti-PD1 are standard treatments for many solid tumors, TIGIT and LAG3 have emerged as promising new targets for cancer immunotherapy." (PMID 40067762, 2025). "While the therapeutic potential of aptamers targeting TIGIT, VISTA, and B7-H3 is being explored in cancer immunotherapy, the data available on these aptamers is limited." (PMID 40870970, 2025). "TIGIT is an inhibitory receptor expressed on the surface of CD4+ and CD8+ T cells and NK cells, and it is targeted in cancer." (PMID 40371640, 2025). "In line with increased infiltration of cluster #2 cancers by T cells, clinically relevant immune checkpoint genes CTLA4, TIGIT, and PDCD1 were found to be expressed in this cluster at the highest levels." (PMID 40011822, 2025). "In summary, the current clinical trials related to targeted cancer metabolism encompass a diverse array of drugs and targets, including KRAS G12C, HER2, Trop-2, PD-1/PD-L1, TIGIT, and NTRK fusion genes." (PMID 39744225, 2025). "In chronic infections (e.g., HIV, HCV) and cancer, multiple coinhibitory receptors, including PD-1, CTLA-4, LAG-3, TIM-3, and TIGIT are upregulated on Tex." (PMID 40236693, 2025). "Downregulation of FOXP3 in cancer Tregs was accompanied by significantly decreased mRNA expression of five out of nine tested exhaustion markers: CTLA-4, Tim-3, PD-1, LAG-3 and TIGIT in the endogenous T cells." (PMID 39234236, 2024). "Then, immune checkpoints analysis shown that UBE2C had a negative correlation with immune checkpoints, such as CD274(PD-1), PDCD1(PD-L1), CTLA4, TIGIT, LAG3, HAVCR2, and PDCD1LG2 in a great many cancers." (PMID 38370368, 2024). "Other receptors, such as CTLA-4, TIM-3, TIGIT, and CD96, should be studied more thoroughly for their potential clinical targeting for cancer immunotherapies." (PMID 39339180, 2024). "The findings revealed that 22 genes, including key immune checkpoint molecules such as PDCD1, TIGIT, and LAG-3, were significantly upregulated in hot tumors across all five cancer types." (PMID 39911580, 2024). "TIGIT, CTLA-4, PD-1, T cell immunoglobulin 3 (Tim3), and lymphocyte activation gene 3 (LAG3) are the most commonly targeted checkpoints for cancer immunotherapy." (PMID 39349422, 2024). "Drugs directed against TIGIT, ILT4, LAG-3, TIM-3 or therapeutic cancer vaccines are currently being studied in early-phase clinical trials, showing promising results." (PMID 39407796, 2024). "We investigated the methylation levels (beta values) of TIGIT, CXCL13, LAYN, LAG3, PDCD1, and HAVCR2 across different cancer types." (PMID 39064019, 2024). "TME of RMS is notably immunosuppressive, marked by an abundance of regulatory T cells (Tregs) and the expression of immune checkpoint molecules such as TIGIT, which interact with NECTIN3 on cancer cells, potentially leading to T‐cell dysfunction." (PMID 39658531, 2024). "We initially explored the expression of the Tex signature genes (LAG3, TIGIT, LAYN, PDCD1, HAVCR2, and CXCL13) in pan-cancer." (PMID 39064019, 2024).
cancer (continued). "The specific blockade of the CD155 interaction with multiple inhibitory receptors expressed on NK and T lymphocytes, such as TIGIT, killer-cell immunoglobulin-like receptor (KIR) KIR2DL5 and CD96, are now being explored in various types of cancer." (PMID 39682686, 2024). "We anticipate that the combining anti-TIGIT and anti-LAG-3 dual target therapy will be a novel approach to cancer immunotherapy." (PMID 38724599, 2024). "Epithelial cancer cells, through the PD-1/PD-L1 pathway, and mesenchymal cancer cells, through the CTLA-4/CD80 and TIGIT/CD155 pathways, differentially block antitumor immune responses and determine the response to ICB therapies." (PMID 38914547, 2024). "In vivo, PVR binds to TIGIT and inactivates CD8+ T cells, and targeting PVR-TIGIT promotes CD8+ T cell responses and improves survival in cancer-bearing mice." (PMID 39156900, 2024). "Because CD155 can bind to CD226, a receptor expressed on T cells and NKs, and result in the stimulation of T cells and NKs, TIGIT competes with CD155, leading to an overall immunosuppressive phenotype and poor overall survival in cancer patients." (PMID 38257366, 2024). "In contrast, EpCAMlow, EpCAM− and full mesenchymal cancer cells downregulated the expression of PD-L1, CD112, and Gal9, and upregulated the expression of CD80 and CD155, ligands of CTLA-4 and TIGIT, respectively." (PMID 38914547, 2024). "It is conceivable that the fusion WT NVs platform can be extended to concurrently targeting to other checkpoints for synergetic cancer immunotherapy except PD‐1/PD‐L1 and SIRPα/CD47, such as CTLA‐4, LAG‐3, TIGIT and so on." (PMID 37974395, 2023). "For instance, ICOS has positive relationships with PDCD1, TIGIT, CD274, and CTLA4 in the majority of cancer types, indicating a broad co-expression landscape." (PMID 36855091, 2023). "This is evident in the rejection of carcinogen-exposed DMBA3-4 cells mixed with control cancer cells, which is achieved by anti-CSF1R and anti-TIGIT combination treatment." (PMID 37843274, 2023). "The close relations of nectins to TIGIT, CD96 and CD226 make them an interesting target for immunotherapy of cancers." (PMID 37568798, 2023). "In this study we provide preclinical evidence that strongly supports the clinical development of multispecific checkpoint inhibitors targeting PD-L1, TIGIT, and LAG-3 as promising cancer immunotherapy agents." (PMID 37332070, 2023). "Several studies have reported that NK cells obtained from cancer patients or patients with chronic infections had lower expression of DNAM-1 and/or TIGIT." (PMID 37345049, 2023). "In preclinical studies, TIGIT and LAG-3 inhibitors are effective in combination with PD-1 inhibitors in various cancer models, such as melanoma, lung cancer, and ovarian cancer." (PMID 37031434, 2023). "More recently, a study further identified nectin-4 as a cancer-specific ligand of the inhibitory receptor T-cell immunoreceptor with Ig and ITIM domains (TIGIT), and their interaction was found to inhibit the antitumor activity of nature killer (NK) cells." (PMID 38288120, 2023). "Exhausted T cells in cancer express high levels of inhibitory receptors, including PD-1, CTLA-4, TIM-3, LAG3, BTLA, and TIGIT, most of which are also known as Treg markers." (PMID 36901957, 2023). "In this review, the role of five ICs, viz., VISTA, TIGIT, LAG-3, TIM-3, and PD-1, will be examined in cancer progression, metastasis, and clinically refractory cases." (PMID 37345111, 2023). "Several inhibitory immunoreceptors have been discovered and studied in cancers, and apart from PD-1 also include CTLA-4, LAG3, TIM3, TIGIT, BTLA, etc." (PMID 38067344, 2023). "A number of inhibitory immunoreceptors have been identified and studied in cancer in past decades, including but not limited to PD-1, PD-L1, CTLA-4, LAG3, HAVCR2, TIGIT, CD69 and CD40." (PMID 37989761, 2023).
cancer (continued). "Despite the beneficial effects of radiotherapy and some immunogenic drugs, the exposure of Tregs, DCs, TAMs, and also cancer cells to some DAMPs such as adenosine lead to overexpression of some co-inhibitory molecules such as Tim-3, CTLA4, TIGIT, and PD-L1." (PMID 37221555, 2023). "Research into further immunotherapeutic candidates is currently thus at the forefront of cancer research; one such candidate molecule is ‘T cell immunoglobulin and ITIM domain’ (TIGIT)." (PMID 37325585, 2023). "To date, attempts to modulate these immunoregulatory pathways have been centered around TIGIT antagonism and/or CD226 agonism in the context of cancer immunotherapy utilizing antibodies, with mixed results being observed in clinical trials." (PMID 36944702, 2023). "The adenosine A2A and A2B receptors, CD47-SIRPα, TIM-3, LAG-3, TIGIT, and VISTA are targets that also contribute to cancer immunoresistance and have been considered for clinical trials." (PMID 36829496, 2023). "To date, TIGIT antibody antagonists have been developed to restore immune functions and allow PVR to signal though CD226 in the context of cancer immunotherapy." (PMID 36944702, 2023). "T cell immunoreceptor with immunoglobulin and ITIM domain (TIGIT) (also known as VSIG9, Vstm3, and WUCAM) is a coinhibitory receptor belonging to the immunoglobulin superfamily 9 and has sparked enormous interest in relation to cancer immunity." (PMID 37649613, 2023). "In cancer progression, CD226 was negatively regulated by TME-driven immune suppression, while IFNG and TIGIT were highly expressed in specific TILs." (PMID 37056782, 2023). "To test this possibility, we incubated cancer cells (RKO that express endogenous PD-L1) with Jurkat T cells that express LAG-3 or TIGIT, in the presence of GB265, GB266, GB266T, or control monospecific antibodies." (PMID 37332070, 2023). "TIGIT protein expression is abundant in CD4+/CD8+ TILs and Tregs from a wide range of cancer types and is often correlated with poor clinical outcomes or resistance to ICI therapies." (PMID 37928556, 2023). "We next performed multiplex IHC to assess coexpression of TIGIT + on CD8 + T cells and PVR + on CK19 + cancer cells at the protein level." (PMID 36781852, 2023). "Cancer cells and cancer antigen-presenting cells express CD155 and CD112, which bind TIGIT, decreasing T cell activity, and coordination with PD-1 or PD-L1 inhibitors shows promising early results." (PMID 37221584, 2023). "Strong preclinical evidence supports blocking the TIGIT pathway for cancer immunotherapy, although a recent Phase III clinical trial of anti-TIGIT tiragolumab combined with anti-PD-L1 (Tecentriq) failed." (PMID 37332070, 2023). "On contrary, TIGIT+NK cells display greater cytolytic molecules but lower IFN-γ expression in HIV-infected individuals and cancer patients." (PMID 37006235, 2023). "Other immune checkpoints, including LAG‐3, TIM‐3 (also known as HAVCR2), TIGIT, and VISTA, have emerged as promising targets in cancer immunotherapy." (PMID 37904707, 2023). "Since immune checkpoint inhibitors (ICIs) have been a prominent topic in cancer treatment, the expression of eight ICIs (LAG3, HAVCR2, CD27, TNFRSF14, CTLA4, TMIGD2, TIGIT, and PDCD1LG2) were analyzed between groups in the study." (PMID 37405988, 2023). "On the other hand, the regulation of co-inhibitory molecules such as PD-L1, Tim-3, TIGIT, and CTLA4 by cancer cells, Tregs, TAMs, DCs, and MDSCs can exhaust the anticancer potency of cytotoxic CD8 + T lymphocytes." (PMID 37221555, 2023). "Intriguingly, the expressions of TIGIT and CD28 were positively correlated with those of DDR1 in LAML and LIHC but negatively correlated with those of DDR1 expression in the other 17 cancers." (PMID 37031216, 2023). "Interactions of the immune checkpoint molecules LAG3‐LGALS3 and TIGIT‐NECTIN2 between CD8+ T cells and cancer/immune/stromal cells are found to play dominant roles in the immune escape." (PMID 36529697, 2023).
cancer (continued). "TIGIT interacts with different ligands, such as CD155 and CD112, which are highly expressed on cancer cells, leading to the suppression of immune responses." (PMID 37109579, 2023). "Accordingly, CD226 agonism in combination with appropriate antagonistic anti-TIGIT and/or anti-CD96 antibodies represents an attractive therapeutic strategy in the context of cancer immunotherapy." (PMID 36944702, 2023). "For example, the top 15 hub genes in T cells from all types of cancers included those involved in cell-mediated immunity (GZMB, PRF1 and IFNG) and immune checkpoint signaling pathways (TIGIT and CTLA4)." (PMID 36350625, 2023). "Both the TIGIT/CD155/DNAM-1 axis and the programmed cell death pathway play role in T-cell exhaustion, and TIGIT and PD-1 are co-expressed on CD8+ T cells in human cancer." (PMID 36497240, 2022). "This demonstrates that TIGIT expression is acquired by MCL cells after BA relapse, and this has not yet been reported in any patients with hematologic malignancies or other cancer types after CAR T-cell therapy." (PMID 36163179, 2022). "We examined the correlation between the transcriptomic expression of SPINK1 and a number of critical ICPs—PD-1, LAG-3, TIM-3, TIGIT, and CTLA-4—which are the likely signatures for the response to ICB in cancer immunotherapy." (PMID 35924241, 2022). "In particular, over-expression of CD155 in cancer is recognized by a group of receptors, including DNAM-1, TIGIT, and CD96, expressed on T and NK cells, which further transmit an alert signal to the immune system during malignant transformation." (PMID 36309698, 2022). "The checkpoint inhibitor TIGIT (T cell immunoreceptor with immunoglobulin and ITIM domain) plays a critical role in immune evasion of cancers via binding CD112 (PVRL2 or nectin-2), one of two TIGIT ligands." (PMID 35681785, 2022). "For example, Fap2 is an important OMP encoded by the Fap2 gene of F. nucleatum that participates in the binding of F. nucleatum to cancer cells and to interact with the immunoglobulin and ITIM domain (TIGIT) receptor mainly expressed on T cells and NK cells." (PMID 35574378, 2022). "AP3S1 expression was positively correlated with most immunosuppressive genes in pan-cancer, such as the common CD274 (PD-L1), PDCD1 (PD-1), CTLA4, LAG3, and TIGIT." (PMID 35874816, 2022). "We also assessed the correlations between DAAM2 and the expression of immune checkpoints, including TIGIT, CTLA4, CD274, and PDCD1, across cancers." (PMID 35281277, 2022). "Other immunoreceptors extensively studied in cancer are LAG-3, TIGIT, T-cell immunoglobulin and mucin containing protein-3 (TIM3) and B and T lymphocyte attenuator (BTLA)." (PMID 35211124, 2022). "TIGIT (T-cell immunoglobulin and ITIM domain) has emerged as a promising target in cancer immunotherapy." (PMID 35273608, 2022). "In a clinical trial, patients with cancer with NSCLC who received oral calcitriol (1α,25(OH)2D3) showed decreased cell-surface level of PD-1, Tim-3 and TIGIT and increased CD28 expression on Vγ9Vδ2+ and CD8+ T cells." (PMID 35318258, 2022). "The emergence of immunotherapy has shed light on cancer therapy; TMB and immune checkpoints, such as PD-L1, CTLA-4, LAG3, TIM3, and TIGIT, act as gatekeepers or biomarkers of immune responses." (PMID 35493104, 2022). "PVRIG is a co-inhibitory receptor of the DNAM/TIGIT/CD96 family and binds to PVRL2, both abnormally expressed in human cancers." (PMID 35641998, 2022). "We also demonstrated that TMEM59L expression was negatively linked with the expression of many immune modulators, including PD-L1, IDO1, TIGIT, CTLA-4, and BTLA in various cancers." (PMID 36618425, 2022). "Our findings brought to light that PTX3 had a close and positive association with most ICIs (CD274, CTLA4, HAVCR2, LAG3, PDCD1, PDCD1LG2, TIGIT, and SIGLEC15) in TCGA cancers, except TGCT." (PMID 36139597, 2022). "TIGIT/CD155 has attracted widespread attention as a new immune checkpoint and a potential target for cancer immunotherapy." (PMID 35729552, 2022).
cancer (continued). "By virtue of the clinical progression of TIGIT antagonists and emergence of novel CD96- and PVRIG-based approaches, our overall understanding of the ‘CD226 axis’ in cancer immunotherapy is starting to take shape." (PMID 35812451, 2022). "Other potential immune checkpoints, such as LAG3, CD96, PDCD1, BTLA, IDO1, and TIGIT, were also enriched in PTPRD/PTPRT mutant cancers." (PMID 36248841, 2022). "AP3S1 expression was positively correlated with most immunosuppressive genes in pan-cancer, such as CD274 (PD-L1), PDCD1 (PD-1), CTLA4, LAG3 and TIGIT." (PMID 35874816, 2022). "We propose that the TIGIT/CD155 axis mediates resistance to ICIs in patients with cancer with inflamed TME, including acquired resistance, and that TIGIT blockade therapies should be developed for such patients." (PMID 34795004, 2021). "Both clusters also exhibited a cancer-specific exhaustive signature characterized by higher expression of checkpoint molecules (CTLA-4, LAG3, TIGIT)." (PMID 34921160, 2021). "Dysregulation of the TIGIT/CD96/CD226/CD155 axis and NK cell function has been observed in certain cancers." (PMID 33946954, 2021). "TIGIT binds to three ligands, namely CD155 (PVR), CD112 (Nectin-2), and CD113 (Nectin-3), that are expressed on APCs and cancer cells." (PMID 34948104, 2021). "Here, we analyzed the The Cancer Genome Atlas (TCGA) transcriptomic database and identified PD1 and TIGIT as top putative targets for GBM immunotherapy." (PMID 34025646, 2021). "Previous review has elucidated the mechanism of CD226/TIGIT/CD96 pathway, addressing the important role of these membrane-sided signal receptors in multiple cancer types." (PMID 33680972, 2021). "Unfortunately, cancer cells can take advantage of checkpoints such as CTLA-4, PD-1, TIGIT and indoleamine 2, 3-dioxygenase 1 (IDO1) to evade the immune response." (PMID 33262461, 2021). "NKG2A, TIGIT, CD96 along with the PD-1 are now well acknowledged immune checkpoints on NK cells, suggesting that they are potent candidates for cancer immunotherapy." (PMID 33262461, 2021). "Our results not only showed the positive correlation of TIGIT with MSI/TMB in COAD, but also revealed more correlations between TIGIT expression and MSI/TMB in multiple other cancer types at pan-cancer level, such as in UCSC." (PMID 34795387, 2021). "CD226 downregulation has been reported in T or NK cells of patients with cancer or human immunodeficiency virus (HIV), which most likely occurs with an upregulation of PD-1 and TIGIT and impaired functionality." (PMID 33670993, 2021). "Our results also revealed the correlation of TIGIT with pathological stages in KIRC, KIRP, and UVM these 3 cancer types with prognostic values." (PMID 34795387, 2021). "New therapies that target other co-inhibitory receptor pathways belonging to the nectin and related families (such as CD96, T cell immunoglobulin and ITIM domain (TIGIT), and CD112R) have been validated in cancer immunotherapy." (PMID 34507594, 2021). "TIGIT, T cell immunoglobulin and ITIM domain, is an inhibitory immunoreceptor and an interesting cancer immunotherapy target." (PMID 33796525, 2021). "The inhibitory checkpoint receptors TIGIT (T cell Ig and ITIM domain) and CD96 are upregulated by T and NK cells following activation when exposed chronically to antigen in settings like cancer." (PMID 34150627, 2021). "Among these, in the present study, we focus on the roles of TIGIT and CD226 in regulating T and natural killer (NK) cell function and the potential therapeutic application of these receptors in cancer immunotherapies." (PMID 33670993, 2021). "TIGIT and CD96 receptors are expressed by T- and NK-cells after activation by chronic antigen exposure, for example, in malignant tumors." (PMID 34943606, 2021). "T cells in the TME of advanced cancer showed increased expression of PD1, CTLA4, CD39, PD-L2, LAG3, TIGIT, Tim3 and decreased expression of CD73." (PMID 34135436, 2021).